ENSG00000258790 (novel transcript)
Gene: Protein-coding gene on chromosome 14 (35,122,549 to 35,317,474, forward strand). Ensembl gene ENSG00000258790.
Genetic constraint (gnomAD): Missense variants: 564 observed, 641.21 expected, observed/expected ratio (o/e) 0.88, 90% interval 0.82 to 0.94. Synonymous variants: 207 observed, 235.41 expected, observed/expected ratio (o/e) 0.88, 90% interval 0.78 to 0.99.